MYC (MYC proto-oncogene, bHLH transcription factor)
Diseases named in the same sentence as MYC in open-access papers (continued):
Sharing a sentence is not in itself a finding about the gene and the disease.
tumor (continued). "MYC over-expression was found in 980 (69%) of CRCs and was associated with tumor stage and DNA mismatch repair/BRAF status." (PMID 24503701, 2014). "This work focused on the BAR adapter-encoding gene BIN-1, a tumor suppressor previously found to be downregulated in several transformed cell lines and demonstrated to suppress the transformational activity of MYC by interacting with its N-terminus." (PMID 25339948, 2014). "In conclusion, our study report novel findings showing that PLA2R1 is repressed in RCC by the loss of VHL tumor suppressor and the activation of the oncogenic HIF2α-c-MYC pathway and that repression favors RCC tumorigenecity." (PMID 24657971, 2014). "In mouse models, c-MYC overexpression causes tumor formation in different cell types and inactivation of expression reverses tumorigenesis." (PMID 23634284, 2013). "An increased MYC mRNA expression was associated with deeper tumor extension (p = 0.006, η2 = 0.152, OP = 0.801), presence of lymph node metastasis (p = 0.023, η2 = 0.107, OP = 0.632), and distant metastasis (p<0.001, η2 = 0.788, OP = 1)." (PMID 23717612, 2013). "Aberrant MYC signaling in cancers is associated with poor clinical outcomes, increased rates of metastasis, tumor recurrence, and patient mortality." (PMID 25374893, 2013). "MYC immunostaining was also associated with late-onset (p = 0.026, OR = 3.276; CI 95% = 1.152–9.315), deeper tumor extension (p = 0.045, OR = 2.975, CI 95% = 1.027–8.623), and the presence of distant metastasis (p<0.001, OR = 17.682, CI 95% = 3.914–79.882)." (PMID 23717612, 2013). "Our results showed decreased levels of survivin and MYC, genes associated with tumor progression, and HIF1A and VEGFR2m, that are associated with tumor progression and angiogenesis in the cabozantinib–treated C4-2B tumors." (PMID 24205338, 2013). "It is well known, that tumor cell proliferation is associated with an upregulation of oncogenes like MYC and that the inactivation of MYC can revert the neoplastic phenotype and induce apoptosis." (PMID 23874405, 2013). "MYC is expressed at high levels in most tumors, and several tumor types also contain translocations, amplifications, and mutations in key MYC regulators." (PMID 25374893, 2013). "The gain of MYC copies was associated with late-onset, intestinal-type, advanced tumor stage, and the presence of distant metastasis (p<0.05)." (PMID 23717612, 2013). "Recent identification of CIP2A as a cancer-associated protein that inhibits PP2A activity towards MYC shed light on the previously unanswered question of how PP2A tumor suppressor activity is regulated in cancer cells." (PMID 22461891, 2012). "Although these findings will require confirmation in additional, independent tumor cohorts, our results indicate the feasibility and utility of IHC staining for MYC that can be implemented as part of the standard diagnostic evaluation of DLBCL." (PMID 22511926, 2012). "Clinically, c-MYC expression levels in OS tumour samples was linked to resistance to methotrexate, with high c-MYC expression correlating to worse outcomes in OS patients." (PMID 23036272, 2012). "Expression of MYC is deregulated in a wide range of human cancers, and is often associated with aggressive disease and poorly differentiated tumor cells." (PMID 22132187, 2011). "A recent article by Gordan addressed this crucial question and suggested that HIF2 enhances c-MYC activity and promotes tumor progression in VHL deficient tumors." (PMID 21756335, 2011). "This cluster of miRNAs was reported as potential oncogenes in various tumours, with its elevation being caused by genome amplification or by transcriptional activation by MYC." (PMID 22045190, 2011). "We show that focal c-MYC expression cooperates with Pten heterozygosity to promote tumor progression due to the selection of cells with loss of Pten expression." (PMID 19578399, 2009).
tumor (continued). "We have also analyzed mice in which prostate epithelial cells with two mutations (c-MYC overexpression and loss of Pten tumor suppressor) are found next to cells with a single mutation (loss of Pten)." (PMID 19578399, 2009). "Deregulated or elevated expression of c-MYC has been documented in a wide range of human malignancies and is often associated with tumours of an aggressive, poorly differentiated phenotype." (PMID 18493233, 2008). "In turn, the transactivation of β-catenin increases the transcription of genes that promote tumor cell growth, such as MYC, CCND1 (which encodes cyclin D) and JUN." (PMID 17764575, 2007). "High tumour vascularity correlates with metastatic disease, MYC amplification, unfavourable histology and poor outcome; by contrast, low tumour vascularity is associated with favourable prognostic features, such as localised disease and favourable histology." (PMID 16721359, 2006). "The activation of MYC during embryonic development and at birth caused gross liver enlargement and rapid emergence of neoplasia." (PMID 15455033, 2004). "Moreover, transcription factor activity analysis revealed elevated activity of several transcription factors, such as ARID2, E2F1, E2F4, NFYB, and MYC, in the RRhighepi group, all of which are closely associated with cell proliferation and tumor progression." (PMID 41424847, 2026). "High MKI67+ tumor cell percentage was associated with better cancer-specific survival, an antitumorigenic immune microenvironment, downregulation of epithelial–mesenchymal transition, and upregulation of MYC signaling." (PMID 41201451, 2026). "Our method leverages ex vivo tumor cell modification, which may mitigate systemic toxicities associated with MYC inhibition." (PMID 40552293, 2025). "Dysregulation of c-MYC is a hallmark of many human cancers, where its overexpression drives malignant transformation and tumor progression by activating a broad transcriptional network controlling ribosome biogenesis, nucleotide synthesis, and metabolic reprogramming." (PMID 41349769, 2025). "As with other mutations associated with SCLC transformation, MYC amplifications are often present in the pre-transformed NSCLC tumor, suggesting this may predispose certain patients to SCLC transformation." (PMID 39858043, 2025). "Nevertheless, due to the extensive regulation of cellular gene expression by MYC and the incomplete understanding of the mechanisms underlying tumor immune escape, the precise pathways through which MYC influences tumor immune evasion remain inadequately elucidated." (PMID 40732268, 2025). "In addition to promoting tumorigenesis, MYC is also required for tumor maintenance; inhibiting MYC in mouse models causes dramatic tumor regression, making it an attractive anti-cancer target." (PMID 40487451, 2025). "NHWD-870 has many beneficial properties, including inhibition of tumor proliferation by inhibiting BRD4 and c-MYC transcription, inhibition of tumor-associated macrophages (TAM) development, and reduction of CSF-1 (colony-stimulating factor) secretion by tumor cells." (PMID 40650308, 2025). "Furthermore, overexpression of c‐MYC led to increased microRNA 17/20a expression which caused downregulation of macrophage colony‐stimulating factor 1 and reduction in tumor infiltrating macrophages." (PMID 41170752, 2025). "Notably, PDH-mediated proline catabolism is associated with tumor survival and metastasis, while MYC’s regulation of both proline synthesis and degradation highlights the oncogenic control over this metabolic pathway." (PMID 40535116, 2025). "Moreover, the observation that GCN2 inactivation is detrimental to certain cancer cells while at the same time leading to the induction of MYC targets and protein anabolism, typically linked to tumour growth, is intriguing." (PMID 40032489, 2025).
tumor (continued). "MYC family transcription factors play a key role in the development and progression of human cancers, and alterations in MYC oncogenes are a hallmark of many human cancers, supporting the process and progression of tumor, and elevated MYC levels are also associated with resistance to therapy." (PMID 40519919, 2025). "MYC multimers stabilize the connection of replication fork-associated proteins and chromatin, thereby protecting the integrity of DNA double-stranded structures and promoting tumor cell proliferation under stress conditions." (PMID 40290126, 2025). "The high expression of DNMT1 in tumor cells was previously linked to the binding of MYC to the DNMT1 promoter region and subsequent activation of its transcription, where DNMT1 can be further recruited by enhancer of EZH2 to methylate the promoter sequence of tumor suppressors." (PMID 40317882, 2025). "Specifically, GSEA analysis revealed significant activation of MYC and mTORC1 signaling pathways in the high-risk group, which are known to reshape the tumor immune microenvironment, suppress T cell function, and promote myeloid-derived suppressor cell accumulation." (PMID 39925852, 2025). "However, during tumor progression, MYC can be mutated or overexpressed, promoting tumor development." (PMID 39852139, 2025). "Furthermore, gene set enrichment analysis (GSEA) showed that USP7 knockdown is significantly associated with the inhibition of tumor formation by downregulating the genes related to MYC and MAPK3 pathways." (PMID 39840939, 2025). "Additionally, research has found that inhibiting MYC expression in myeloid cells (including macrophages) affects the maturation and pro - tumor activity of tumor - associated macrophages." (PMID 41210882, 2025). "Therefore, in this review, we emphasize the critical role of MYC and MYC-associated oncogenic signaling in tumor immunity and explore potential strategies for targeting MYC in conjunction with immunotherapy." (PMID 40732268, 2025). "In general, tumor regions exhibited significant enrichment in cellular proliferation pathways associated with the G1 phase, such as MYC targets, E2F targets, and G2 phase to mitotic phage (G2M) checkpoints, indicating uncontrolled cell growth within these areas." (PMID 40036264, 2025). "In squamous cell carcinoma (OSCC), elevated CREPT expression was associated with cyclin D1 and c-MYC expression and correlated with pronounced stromal interactions and aggressive tumor behavior, highlighting the crucial role of CREPT in promoting aggressive phenotypes." (PMID 40723282, 2025). "In contrast, the low-response group displayed activity in various pathways, including high enrichment scores for E2F targets related to G2M checkpoints, unfolded protein responses, MYC targets, oxidative phosphorylation, DNA repair, and other functions associated with tumor progression." (PMID 40761787, 2025). "In addition to its direct involvement in promoting cancer, MYC has been linked to various tumor characteristics." (PMID 40732268, 2025). "Overexpression of MYC protein correlates with MYC gene amplification, which is associated with more aggressive tumor behavior and may suggest a poorer prognosis." (PMID 40004808, 2025). "Functional enrichment analysis revealed that pathways predominantly enriched in the high-risk group include MYC gene upregulation, oxidative phosphorylation, and aberrant mitochondrial patterns, all of which are closely associated with autophagy and tumor progression." (PMID 41040512, 2025). "In cancer, the loss of miR-34a expression contributes to tumor progression by allowing the upregulation of oncogenes such as Notch1 (Notch Receptor 1), c-MYC (Cellular myelocytomatosis oncogene), and BCL2 (B cell lymphoma 2), all of which promote cell survival and proliferation." (PMID 40260417, 2025).
tumor (continued). "The MYC oncogene has been widely recognized as a master regulator implicated in numerous hallmarks of cancer, including uncontrolled proliferation, sustained tumor growth, metastasis, immune evasion, and therapy resistance." (PMID 40365020, 2025). "Additionally, our Hallmark gene set analysis revealed that genes in the high-risk group are enriched in pathways such as MYC target genes, G2M checkpoint, and E2F target genes, which are crucial for tumor progression, cell cycle regulation, and proliferation." (PMID 40465746, 2025). "One possible fundamental reason for this diagnostic challenge is that MYC rearrangement may drive B cells to exhibit both tumor proliferative capacity and aberrant immaturity." (PMID 41142614, 2025). "In the presence of c-MYC downregulation, the reliance on low-fidelity polymerases may increase, leading to a higher tumor mutational burden, cancer progression, and resistance to treatment." (PMID 39273190, 2024). "Our results suggest that this loss of function screen not only identified MYC-SL genes but also known and novel tumor suppressor genes, which might play a role in tumorigenesis." (PMID 38302473, 2024). "Additionally, enrichment analysis outlined pathways associated with several cancer hallmarks, including epithelial to mesenchymal transition (EMT) and MYC targets associated with tumour progression." (PMID 39348343, 2024). "In line with the RNA sequencing data, P4BH, FASN, AKR1B1, and CBG5 proteins, which have a high prognostic risk, were upregulated in tumor tissues, and MYC proteins, which have a low prognostic risk, were downregulated in tumor tissues compared with normal controls." (PMID 39749345, 2024). "Given several confounding factors contribute to biological differences between the AYA and OA age groups (for instance, tumour size, grade and histological subtype), following multivariable logistic regression to account for these factors, only the MYC targets hallmark remained significant." (PMID 38762630, 2024). "Some use LNPs to deliver mRNAs that can downregulate the expression of oncogenes, such as the MYC transcription factor, or upregulate the expression of tumor suppressor genes, such as the gene encoding alpha CCAAT enhancer-binding protein (CEBPA, also known as C/EBPα)." (PMID 39065798, 2024). "MYC is a master regulator of gene transcription that is one of the most frequently mutated oncogenes that drives a variety of biological programs to sustain tumor growth." (PMID 38402198, 2024). "Multivariable logistic regression analysis was performed to adjust for potential confounding factors (tumour size, grade, anatomical site, performance status and histological subtype) which led to only the MYC targets hallmark remaining significant between the two age groups (p = 0.047)." (PMID 38762630, 2024). "Regardless of whether EBV is or is not the primary cause of BL, it is clearly a risk factor contributing to carcinogenesis even if the tumor is initiated by a MYC translocation event." (PMID 39766110, 2024). "The transcriptomic analysis results of castration-resistant PCa (CRPC) xenografts sensitive to LSD1 inhibitors show that tumor growth restriction caused by LSD1 inhibition can be attributed to a significant decrease in MYC signal transduction, indicating that MYC is the target of LSD1." (PMID 38605023, 2024). "Furthermore, our analysis revealed that mutations in tumor-related pathways within the high- and low-risk groups were primarily clustered in MYC, RTK-RAS, TGF-Beta, and Cell_Cycle pathways." (PMID 39199281, 2024). "In line with this, a recent study has shown that the MYC overexpression in other tumour types could be driven by the somatic structural variant mediated changes in long‐range chromatin interactions." (PMID 38013620, 2024).
tumor (continued). "Additionally, leveraging multiple datasets and conducting GSEA provided valuable insights into potential associations between DENND2D expression and tumor-suppressive mechanisms, including the regulation of MYC target genes and immune cell infiltration." (PMID 39857609, 2024). "Further, MYC contributes to immune response regulation, and is associated with immune checkpoints, inducing immune evasion of MYC-mediated cancer cells and promoting tumor development." (PMID 37450923, 2024). "Importantly, CAMKV levels were previously correlated to a worse NB patient survival and its expression is highly associated to that of MYCN or MYC in NB cell lines and primary tumor samples." (PMID 38255303, 2024). "On the other hand, MYC oncoproteins are known to drive suppression of tumor immunity, and the top upregulated Hallmark gene sets showed enrichment of IL2_STAT5_signaling, TNFA_signaling_via_NFKB and Hypoxia, all of which have roles in inflammation and immunity." (PMID 38992040, 2024). "Our screen also uncovered tumor suppressor genes whose loss cooperates with MYC to promote cancer." (PMID 38302473, 2024). "However, the role of MYC is context-dependent, as the function of MYC is dependent on post-translational modifications and mutational burdens of its gene targets, and the interaction of the cancer cells with a tumor microenvironment." (PMID 39766097, 2024). "During CRPC development, the tumor undergoes several adaptions counteracting supraphysiological androgen levels, including increased androgen synthesis, AR amplification, AR mutation, AR alternative splicing, MYC overexpression, and hyperactive STAT signaling." (PMID 39199642, 2024). "The deleted MCR harbours 15 genes associated with increased MYC expression in these PMN-WT tumours." (PMID 38877600, 2024). "However, we observed a profound inter- and intratumoral heterogeneity of the expression of DEGs associated with the top enriched pathways in either primary tumor (hypoxia) or metastatic cells (MYC)." (PMID 39225101, 2024). "Interestingly, this family includes two additional genes, b-MYC and s-MYC, that differ from the previous ones because they encode for proteins that suppress tumor growth." (PMID 36979947, 2023). "Based on these findings, it appears that overexpression of USP13 causes an increase in MYC protein during the initial stages of tumor development originating from club cells, which may contribute to the development of LUSC." (PMID 38093367, 2023). "Expression of ERV proteins has been detected in many tumor types, where possible pathogenic mechanisms include activation of the long terminal repeat element into an oncogene with downstream targets such as MYC and vesicular release of viral particles to neighboring cells to maintain pluripotency." (PMID 37173979, 2023). "Hyperactivation of tumor-promoting genes such as MYC and MDM2 is associated with OS tumorigenesis." (PMID 37511127, 2023). "MYC is frequently found deregulated in cancer cells, which are, apart from tumorigenesis-caused genomic instability and epigenetic reprogramming, featured by aberrant activation of proto-oncogenes or inactivation of tumor suppressor genes." (PMID 36969025, 2023). "MYC mutations are hypothesized to be the source of undetermined significance to MM transition, as well as a late genomic event that is responsible for tumor progression." (PMID 37580667, 2023).